MGMT (O-6-methylguanine-DNA methyltransferase)
Diseases named in the same sentence as MGMT in open-access papers (continued):
Sharing a sentence is not in itself a finding about the gene and the disease.
glioblastoma (continued). "Here, we review how DNA methylation of a single gene (i.e., the O6-Methylguanine-DNA Methyltransferase, MGMT, gene) as well as the entire genome (i.e., the methylome) is currently utilized for refining glioblastoma diagnosis, prognosis and treatment." (PMID 35806153, 2022). "Although it has been reported that patients with an IDH mutant glioblastoma and methylated MGMT gene promoter had longer survival than patients with IDH wild-type glioblastoma and an unmethylated MGMT gene promoter; their prognosis remains poor." (PMID 35884887, 2022). "They reported that the ribozyme-SNA complex induced the cleavage of O6-methylguanine-DNA methyltransferase (MGMT) mRNA, downregulated MGMT protein, and increased sensitization of glioblastoma multiforme (GBM) cells to chemotherapy." (PMID 35200353, 2022). "The most prominent candidate with consistent downregulation, was the O-6-methylguanine-DNA methyltransferase (MGMT) gene, a known resistance factor for alkylating agent therapy in glioblastoma." (PMID 36513631, 2022). "Prognostic factors of glioblastoma are age, neurological status, preoperative Karnofsky performance status (KPS), extent of resection, and O6-methylguanine DNA methyltransferase (MGMT) promoter methylation." (PMID 35397757, 2022). "Most G-I-CC were glioblastomas (84.5%) with IDH-wildtype (84.9%) and unmethylated MGMT promoter (53.5%)." (PMID 35626112, 2022). "The epigenetic silencing of the MGMT gene by promoter methylation compromises DNA repair, improving response to TMZ and leading to longer survival of glioblastoma patients." (PMID 35954371, 2022). "Indeed, glioblastoma (GBM) patients with positive VM possess shorter survival times than VM-negative patients, even in patients with MGMT promoter methylation." (PMID 34976814, 2021). "In the IDH-wildtype glioma group (i.e., glioblastoma, low-grade glioma MYB/MYBL1 and (anaplastic) pleomorphic xanthoastrocytoma), MGMT promotor was methylated in 29% (5/17) and unmethylated in 71% (12/17) of the cases." (PMID 33941250, 2021). "This means that glioblastoma with wildtype IDH1 and unmethylated MGMT promoter should be treated aggressively with combined chemotherapies (TMZ plus other chemotherapies) to improve overall survival." (PMID 34257620, 2021). "Histopathological analysis confirmed the suspected diagnosis of glioblastoma (WHO IV) and methylation status of MGMT gene promoter." (PMID 34067871, 2021). "O6-methylguanine-DNA methyltransferase (MGMT) promoter methylation, a marker that predicts response to temozolomide chemotherapy in glioblastoma, is one example that is already implemented in a clinical setting." (PMID 34572523, 2021). "Promoter meythlation of the O6-methylguanine-DNA methyltransferase (MGMT) and IDH1/IDH2 has a particularly high prevalence in LGG, and methylation of the MGMT promoter is predictive for treatment response in glioblastoma patients." (PMID 34277415, 2021). "In the DIRECTOR study where first glioblastoma recurrences were treated with different temozolomide dose regimens, PRS ranged between 7.9 months for MGMT-unmethylated and 12.5 months for MGMT-methylated tumors." (PMID 33917116, 2021). "Currently, the biomarkers for glioblastoma are mostly molecular and include EGFRvIII, ATRX, PTEN, IDH1, MGMT, and others." (PMID 34462698, 2021). "The MGMT is recognized as a biomarker, as well as a primary contributor to TMZ resistance in glioblastoma." (PMID 34724914, 2021). "The effects of TMZ treatment on U87 cell viability and resistance-related gene expression (MGMT and ABCB1) were used to validate and compare our long-term 3D with 2D glioblastoma cell culture." (PMID 34439644, 2021). "Studies on the epidemiology of oligodendroglioma diagnoses and testing for O-6-Methylguanine-DNA Methyltransferase (MGMT) promoter methylation in glioblastoma (GBM) patients may provide further insights into disparities in molecular testing rates." (PMID 34858822, 2021).
glioblastoma (continued). "Our results demonstrated that besides MGMT, ABCB1 expression also increases in 3D glioblastoma cell culture more profoundly than in 2D." (PMID 34439644, 2021). "The methylation status of MGMT and THBS1 in CSF was also able to independently predict PFS of glioblastoma patients." (PMID 34208598, 2021). "Although minor changes between primary material and PDXs have been observed, most of the models appear to have conserved the key characteristics of glioblastoma (CSC expression, histology, MGMT promoter methylation)." (PMID 32260145, 2020). "In a Japanese study, the incidence of MGMT promoter methylation was 36% in grade III gliomas and 46% in glioblastomas." (PMID 32005184, 2020). "Nevertheless, our findings, showing that MPG may be associated with TMZ resistance in human glioblastoma cells, could encourage and enable further research related to development of new therapeutic approaches to TMZ resistance using the enzyme MPG as a possible target along with MGMT." (PMID 33335215, 2020). "MGMT promoter methylation is a predictive marker of response to alkylating agent temozolomide (TMZ), a routinely used chemotherapeutic agent in glioblastoma treatment." (PMID 33053907, 2020). "We spared chemotherapy in likely non-responder patient population such as elderly or frail glioblastoma (GBM) patients with unmethylated MGMT promoter, as well as taking into account an hypofractionated radiotherapy approach to reduce the number of patients' access to the Hospital." (PMID 33330558, 2020). "The MES subtypes BTSC233 and JHH520 followed in drug sensitivity, finally followed by the pediatric glioblastoma model SF188, which was the most sensitive and only MGMT-unmethylated cell line used." (PMID 33371210, 2020). "With the discovery of methylation of O6-methylguanine-DNA methyltransferase (MGMT) that sensitizes glioblastoma multiforme (GBM) cells to temozolomide, epigenetic alterations have been extensively studied to uncover the molecular mechanism behind therapy resistance." (PMID 33718113, 2020). "Herein, we performed in vitro and in vivo experiments, six human IDH1/2 wild-type glioblastoma stem-like cells (GSCs) were established and studied to further determine a potential interaction of YKL-40 and MGMT promoter methylation." (PMID 32820151, 2020). "We also observed a consistent trend with the glioblastoma cohort, namely, a low level of ALDOC expression in the unmethylated MGMT and IDH1 wild-type group (p < 0.0001, p < 0.0001, respectively)." (PMID 31450822, 2019). "Two glioblastoma xenograft lines, GBM12_3080 and GBM12_5199, both exhibit MGMT promoter methylation, but the FM-HCR assay correctly assigns GM12_3080 to be MGMT proficient, consistent with previous independent characterization." (PMID 30811507, 2019). "Particularly, survival prediction of glioblastoma based on combination of IDH1 and MGMT methylation status outperforms the prediction by either of the biomarkers." (PMID 31150499, 2019). "We collected information of survival time, MGMT methylated status, CIMP status, and IDH1 mutant status from TCGA glioblastoma cohort." (PMID 31450822, 2019). "Glioblastoma (GBM) is the most common malignant central nervous system tumor, and MGMT promoter hypermethylation in this tumor has been shown to be associated with better prognosis." (PMID 30774763, 2019). "Notably, MGMT defects occur in many cancers including glioblastoma, colorectal cancer, leukemia, lymphoma, small cell lung cancer, breast cancer, pancreas cancer, and melanoma, and in some cases increases the effectiveness of therapeutic agents that generate DNA lesions that are MGMT substrates." (PMID 30811507, 2019).
glioblastoma (continued). "In this study, we characterized the modulating effects of FM19G11 on O6‐methylguanine DNA‐methyltransferase (MGMT), the main regulator of temozolomide (TMZ) resistance in glioblastomas." (PMID 29761922, 2018). "The rate of MGMT-promoter methylation in Peruvian glioblastoma cases is similar to that described in other races and PCR for its detection in FFPE of glioblastoma samples is an accurate methodology to implement in Latin American countries." (PMID 29515653, 2018). "Velpula et al56 also demonstrated that other mechanisms than MGMT expression can be involved in MDR phenotype, namely in glioblastomas." (PMID 29845734, 2018). "In addition to its role in tumorigenesis, however, MGMT plays a critical role in the cellular response to alkylating agents; its epigenetic silencing via methylation is a strong predictive biomarker for response to alkylating agents in glioblastoma, colorectal cancer, and Hodgkin lymphoma." (PMID 30120226, 2018). "Currently, glioblastoma STS can to some extent be identified using molecular markers e.g. IDH, MGMT, and TERT." (PMID 29136645, 2017). "We were able to validate previous findings describing frequent hypermethylation events of EPHA7, MGMT and MLH1 in colorectal cancer patients, RARB in prostate tumors, and CASP8 in glioblastoma." (PMID 28581523, 2017). "In this context, a cut-off value of CHL1 hypermethylation has been established to stratify unmethylated and methylated cases, as seen with MGMT hypermethylation, which has been useful for predicting both PFS and OS in glioblastoma." (PMID 28178655, 2017). "However, in glioblastoma cells not expressing MGMT, resistance to TMZ was shown to be associated with a PI3K–mediated HOX/stem cell gene signature, and this resistance was reversed by inhibition of the PI3K signalling pathway using the dual pan-class I PI3K/mTOR inhibitor PI-103." (PMID 28704425, 2017). "Among the histological types, we evaluated MGMT promoter methylation in 57 astrocytomas WHO II, 13 astrocytomas WHO III and 13 glioblastomas (WHO IV)." (PMID 27834917, 2016). "These miRNAs are also the only candidates from our screen whose levels correlated with MGMT expression in the TCGA and CGGA glioblastoma database." (PMID 27057640, 2016). "The O6-methylguanine-DNA methyltransferase (MGMT), a DNA repair protein involved in the resistance of tumor cells to alkylating agents, is also expressed in glioblastoma and contributes to the resistance to TMZ." (PMID 26956046, 2016). "This method is currently in use in clinical settings for the detection of O6-methylguanine-DNA methyltransferase (MGMT) methylation, which is used as a prognostic and predictive biomarker in glioblastoma treated with alkylating agents." (PMID 27610206, 2016). "The top candidates were further tested for MGMT-suppressing activity and correlation with MGMT expression using the TCGA and CGGA glioblastoma databases." (PMID 27057640, 2016). "Since the introduction of temozolomide (TMZ) chemotherapy in the standard care protocol for glioblastoma (GBM) patients, MGMT promoter methylation analysis has become a crucial biological marker." (PMID 27542245, 2016). "Here, we determined the prognostic value of FZD7 for the overall survival of glioblastoma (GBM) patients, both as individual marker and taken in combination with the previously-described markers MGMT and IDH1." (PMID 27409829, 2016). "The favourable effect of miR-181d-5p was found related at least in part to its effect in down-modulating MGMT mRNA expression in A1207, LN340 and T98G glioblastoma cell lines." (PMID 27057640, 2016). "Since the introduction of temozolomide (TMZ) chemotherapy in the standard care protocol for glioblastoma (GBM) patients, everyone agrees that the analysis of O6-methylguanine DNA methyltransferase (MGMT) status has become a key biological marker." (PMID 26158269, 2015).
glioblastoma (continued). "For example, temozolomide (TMZ) is used to treat glioblastoma, usually in combination with O6-benzylguanine (O6BG) to inhibit methylguanine methyltransferase (MGMT)." (PMID 26702034, 2015). "Further interrogation has revealed the differential expression of MGMT and MSH6 between the subtypes, which suggested the involvement of distinct mechanisms for TMZ resistance during recurrence of glioblastomas." (PMID 26466313, 2015). "MGMT, miR-181d and miR-603 levels were characterized for 74 glioblastoma specimens from the UCSD glioblastoma tumor bank by qRT-PCR; GAPDH was characterized as a control." (PMID 24994119, 2014). "The sensitivity of glioblastoma cells to TMZ is interfered by many factors, such as the expression of O-6-methylguanine-DNA methyltransferase (MGMT) and activation of AKT signaling." (PMID 24265816, 2013). "ZEB1 is preferentially expressed in invasive glioblastoma cells, where the ZEB1-miR-200 feedback loop interconnects these processes through the downstream effectors ROBO1, c-MYB and MGMT." (PMID 23818228, 2013). "Hypo-methylation of the MGMT promoter is correlated with glioblastoma resistance to temozolomide (TMZ) chemotherapy, and consequently with worse prognosis, due to the reduction in TMZ induced alkylation when MGMT is overexpressed." (PMID 23638004, 2013). "We found that the analyzed glioblastoma cell lines (T98G, LN428, U87MG, and A172) expressed different levels of miR-221/222 and displayed a consistent difference in MGMT expression." (PMID 24147153, 2013). "Taken together, further investigation employing larger cohorts will aid the exploration of useful predictors for survival, including MGMT status assessed by various methods and MIB-1 LI, in patients with glioblastoma treated with the combined RT and TMZ." (PMID 24265731, 2013). "Our data argue against any relevant impact of MGMT, ABCB1 or ABCG2 promoter methylation on overall survival of glioblastoma patients." (PMID 24380367, 2013). "A recent study using human tumor cell lines derived from glioblastomas and other tumors concluded that the response to TMZ is better predicted by MGMT protein expression than by promoter methylation status." (PMID 22390413, 2012). "Cox regression analysis showed patient age, treatment, MGMT, GATA6 and CASP8 as independent predictors for glioblastoma patient outcome (p < 0.05)." (PMID 22672670, 2012). "To this end, we investigated methylation of the MGMT promoter by MSP, PSQ and MS-MLPA in 35 FFPE glioblastoma tissues derived from patients treated with dose-intensified TMZ in a prospective clinical phase II trial (UKT-05)." (PMID 22428052, 2012). "MGMT promoter methylation status is widely used to predict the efficacy for combination therapy of RT and TMZ for newly diagnosed glioblastoma." (PMID 22530121, 2012). "The methylation status of MGMT, CD81, GATA6, DR4, and CASP8 in 76 patients with primary glioblastomas was investigated." (PMID 22672670, 2012). "The current study reveals new and important information on MGMT, GATA6 and CASP8 promoter methylation in glioblastoma." (PMID 22672670, 2012). "Gene promoter methylation of the DNA repair enzyme MGMT correlates with clinical response to TMZ treatment in combination with radiotherapy and significantly alters OS of patients with glioblastoma." (PMID 20736948, 2010). "Phase I and II clinical trials in glioma patients have had promising results, especially for patients with hypermethylated MGMT, and cilengitide is currently in Phase III trials in glioblastoma patients treated with radiation therapy and chemotherapy." (PMID 20652056, 2010).
glioblastoma (continued). "Glioblastoma (GB) classical treatment with the alkylating drug temozolomide (TMZ) is not effective mainly due to chemoresistance mechanisms, particularly those mediated by O6-methylguanine-DNA methyltransferase (MGMT)." (PMID 42122682, 2026). "The methylation status of the O6-methylguanine-DNA methyltransferase (MGMT) promoter methylation represents a well-established molecular biomarker for prognosis and a predictive marker of response to alkylating therapy in IDH-wildtype glioblastoma." (PMID 41346390, 2025). "MGMT expression analyses showed MGMT-negative tumor cells, indicative of MGMT promoter methylation in these glioblastoma cases." (PMID 40282990, 2025). "Although MGMT methylation status is not used in the integrated diagnosis of glioblastoma, it remains a critical prognostic tool as there are significant variations in clinical response to standard-of-care treatments (temozolomide) based on the status of MGMT." (PMID 39796751, 2025). "The expression of TXNRD1 was significantly higher in IDH wildtype, 1p/19q non-codeletion, MGMT unmethylation glioblastoma patients in both databases." (PMID 40914135, 2025). "Here, we assessed the potential association between antecedent WBC MGMT methylation state in healthy people and incident colon cancer (CC), glioblastoma (GB), and diffuse large B-cell lymphoma (DLBCL), three tumor forms known to have MGMT epimutations affecting 20–40% of all tumors." (PMID 39980037, 2025). "So far, data on TMT in patients exclusively treated with CCNU and temozolomide as well as exclusively newly diagnosed with MGMT promoter methylated glioblastoma are not available." (PMID 40260649, 2025). "Low or absent MGMT expression in glioblastoma cells can be used as a surrogate marker for the hypermethylation of the MGMT gene promoter." (PMID 40282990, 2025). "Clinical data from our retrospective valganciclovir trials further support its potential to improve survival outcomes in patients with primary, recurrent and secondary glioblastoma, regardless of their MGMT promoter methylation status." (PMID 41194660, 2025). "In line with previous findings that MGMT is a major determinant of TMZ resistance in glioblastoma, our study shows that SQ-TMZ nanoparticles significantly downregulate MGMT expression in TMZ-resistant T98G cells, thereby resensitizing them to alkylating therapy." (PMID 40429865, 2025). "In particular, dovitinib-treated glioblastoma (GB) primary cells and cell lines exhibited downregulation of key base excision repair (BER) factors and O6-methylguanine-DNA-methyltransferase (MGMT), which play crucial roles in repairing temozolomide (TMZ)-induced alkylating DNA damage." (PMID 41154409, 2025). "TMZ, the standard chemotherapeutic agent for glioblastoma, has shown limited efficacy, particularly in the patients lacking O6-methylguanine-DNA methyltransferase (MGMT) promoter methylation or isocitrate dehydrogenase (IDH) mutations." (PMID 40649908, 2025). "At five CpGs in enhancer E, methylation levels were also higher in MGMT expressing glioblastoma samples compared to non-expressing ones (p ≤ 0.05)." (PMID 40244270, 2025). "In intragenic enhancers, both methylation levels at individual CpGs as well as the mean methylation levels across CpGs within the same enhancer were higher in MGMT expressing samples compared to non-expressing glioblastoma samples." (PMID 40244270, 2025). "Genetic modifications in glioblastoma multiforme (GM) encompass EGFR amplification and CDK4 gene changes, deletion of cyclin-dependent kinase inhibitor genes, and silencing of the O-6-methylguanine-DNA methyltransferase (MGMT) gene." (PMID 41322297, 2025). "MGMT expression was positively correlated with USP7 levels in GBM (grade IV) tissues, while both markers exhibited low expression in adjacent normal tissues (p < 0.01, n = 31 paired glioblastoma samples)." (PMID 40835840, 2025).